IL13 (interleukin 13)
Diseases named in the same sentence as IL13 in open-access papers (continued):
Sharing a sentence is not in itself a finding about the gene and the disease.
schistosomiasis (continued). "Type 2 immune response, featured by the T helper 2 cell associated cytokines such as IL-4 and IL-13, is the central regulator of disease progression in schistosomiasis, but the signals that induce it after infection remain elusive." (PMID 29554131, 2018). "A major breakthrough was the identification of type 2 immune response, characterized by the T helper 2 cell associated cytokines such as interleukin 4 (IL-4) and IL-13, as a central regulator of disease progression in schistosomiasis." (PMID 29554131, 2018). "IL-13 is a profibrotic agent and its association with egg-induced immunopathology during schistosomiasis is well documented." (PMID 27152725, 2016). "In this study, we demonstrate a functional polymorphism in IL13, rs1800925 (IL13/-1112C>T), previously associated with risk of schistosomiasis, also increased the risk of development of late-stage schistosomiasis." (PMID 26258681, 2015). "In conclusion, the functional IL13 polymorphism, rs1800925T, previously associated with risk of schistosomiasis, also contributes to risk of late-stage schistosomiasis caused by S. japonicum." (PMID 26258681, 2015). "In this study, we explored the association between IL13 variants rs1800925 and rs20541 and both chronic and late-stage schistosomiasis in a rural Chinese population along the Yangtze River in Hubei province." (PMID 26258681, 2015). "The development of fibrosis in schistosomiasis is dependent on Th2 cytokines, and mice deficient in IL-4/IL-13 fail to upregulate Arg1." (PMID 19360123, 2009). "In addition to TGF-β1, which is the most important regulator for various tissue fibrosis, IL-13 is a critical profibrotic factor in schistosomiasis-associated liver fibrogenesis, exerting its effect independent of TGF-β1." (PMID 39363237, 2024). "One study observed an association between high levels of IL-13 and the CC genotypes in schistosomiasis-uninfected individuals in Zimbabwe, while another study indicated that TT genotypes are correlated with high IL-13 levels in S. japonicum-infected individuals." (PMID 37908348, 2023). "This cross-sectional study was carried out with the primary aim of understanding the interplay between IL-13 gene polymorphisms and Schistosoma infections among schoolchildren in four schistosomiasis-endemic communities in the Central and Ashanti Regions of Ghana." (PMID 34185775, 2021). "These cause the production of the cytokines IL-4, IL-5, and IL-13, which in turn influence Immunoglobulin E (IgE) levels and eosinophilia, components of immune response associated with infection/re-infection resistance in schistosomiasis." (PMID 34185775, 2021). "The IL13 rs1800925 SNP was associated with schistosomiasis in four infection related studies and one pathology study and all studies that included this SNP found an association with it, despite the association not being significant after a Bonferroni correction in any of these studies." (PMID 33659002, 2021). "IL-13 rs1800925 C variant individuals had the highest IL-13 cytokine levels among the schistosomiasis uninfected suggesting that they may be protective against Schistosoma infections." (PMID 34048465, 2021). "The purpose of this study was to evaluate the frequency of promoter gene polymorphisms, to elucidate promoter gene polymorphisms on IL-13 cytokine levels, to determine susceptibility or protection against schistosomiasis and to determine association to risk of prostate cancer development." (PMID 34048465, 2021). "IL-13 may act as an immunosuppressive inflammatory cytokine that may promote carcinogenesis and also may offer protection against schistosomiasis thereby reducing risk of schistosome infections." (PMID 34048465, 2021). "Similarly, IL-13–1112 CT and CC variants had insignificantly higher schistosomiasis burden (mean egg count: 11 (6.0–36.25) eggs/10 mL and 11 (7.0–34.5) eggs/10mL, respectively) compared to TT variants (mean egg count, 9 (4.0–14.0) eggs/10 mL); p = 0.499." (PMID 34048465, 2021).
schistosomiasis (continued). "The experimental Schistosomiasis-associated PAH potentially depends on upregulation of IL-13, which can activate TGF-β1 via phospho-STAT6 signaling, or via increased matrix metalloproteinase-inducing muscular hypertrophy and periadventitial fibrosis in pulmonary arteries." (PMID 34122072, 2021). "One of the objectives of this study was to evaluate schistosomiasis up-regulated inflammatory cytokine IL-13 possibly controlled by IL-13 -1112C/T polymorphisms that could directly or indirectly contribute to prostate carcinoma development." (PMID 34048465, 2021). "Furthermore, IL-13-deficient mice exhibit increased survival time, demonstrating the important role of IL-13 in the pathogenesis of schistosomiasis." (PMID 32132991, 2020). "Signaling by IL-13 and IL-4 has been associate with the severity of schistosomiasis and fibrosis." (PMID 32922381, 2020). "We investigated associations between these and other variants in IL13, covering the full gene (including rs1800925 and rs20541), for two quantitative traits (tIgE levels and S. mansoni egg counts) in a Brazilian population endemic for schistosomiasis." (PMID 22574126, 2012). "Consequently, depending on the duration and magnitude of the infection, Th2 cytokines exhibit both protective (IL-4, acute infections) and pathogenic (IL-13, chronic infections) activity in the mouse model of schistosomiasis." (PMID 19360123, 2009). "IL-13 may contribute to disease burden by increasing eosinophil infiltration and promoting fibrosis but could also protect against infection and reduce the risk of schistosomiasis." (PMID 34048465, 2021). "There are some limitations observed in this study caused by the low number of schistosomiasis infected participants and single nucleotide polymorphisms locus may not have provided us with a clear understanding of the genetic effects of IL-13 on its cytokine productions and risk of prostate cancer." (PMID 34048465, 2021). "We found that IL-13 genotype variants are indicative of IL-13 cytokine concentrations, with the highest levels in schistosomiasis uninfected individuals with heterozygous CT variants compared to the homozygous TT variant of the schistosomiasis uninfected group." (PMID 34048465, 2021). "Schistosomiasis is characterized by a robust Th2 (T-helper 2) immune response, marked by the production of cytokines such as IL-4, IL-5, and IL-13." (PMID 39452777, 2024). "The production of IL-4 and IL-13 from basophils downregulates inflammatory responses in schistosomiasis as these cytokines result in the differentiation of monocytes to alternatively activated macrophages." (PMID 39481080, 2024). "It thus remains largely unclear in these animal studies what effect IL-13 alone has on fibrosis induction by schistosomiasis." (PMID 37629063, 2023). "During schistosomiasis, Th2-derived IL-4/IL-13 contributes to the activation of macrophage-derived TGF-β, leading to severe pulmonary vascular remodeling." (PMID 37908354, 2023). "Other studies highlighted the influence of high concentration of IL-13 during the progression of schistosomiasis due to S. mansoni." (PMID 36889485, 2023). "IFN-γ is a Th1-standard cytokine that, along with IL-12, can protect against the IL-13-mediated fibrosis process in the chronic phase of schistosomiasis." (PMID 36678417, 2023). "Genetic variations in IL13 have been extensively investigated in the context of allergy and asthma and schistosomiasis." (PMID 37908348, 2023). "IL13 and IL4 regulate STAT6 expression which in turn regulates IgE class switching and STAT6 variants are also associated with schistosomiasis." (PMID 33659002, 2021). "Risk of prostate cancer development between participants with prostate-specific antigen levels > 4 ng/mL and < 4ng/mL assessed by IL-13 cytokine concentrations and schistosomiasis status was insignificant X2 (4, n = 66) = 3.996 p = 0.406." (PMID 34048465, 2021).
schistosomiasis (continued). "Levels of IL-13 were significantly different between the IL-13–1112 CC, CT and TT genotypes of the schistosomiasis uninfected individuals (p = 0.022)." (PMID 34048465, 2021). "IL-13 plays a major role in egg granuloma formation during schistosome infections and can stimulate fibroblasts to make collagen leading to fibrosis that may lead to portal hypertension, thus causing much of the morbidity and mortality associated with schistosomiasis." (PMID 34048465, 2021). "Monocytes and macrophages exert important roles during schistosomiasis, while high levels of Th2 cytokines (IL-4 and IL-13) have profound phenotypical and functional impact on these cells." (PMID 32922381, 2020). "The signalling mechanism of IL-13 in schistosomiasis pulmonary vascular pathology is still far from fully appreciated." (PMID 31024947, 2019). "Previously, we found that IPSE/alpha-1 triggers the release of IL-4 and IL-13 from human and murine basophils, suggesting that this molecule is involved in inflammation control in schistosomiasis." (PMID 30364177, 2018). "The cytokine levels of TNF-α, IFN-γ, IL-6, IL-4, IL-5, IL-10, IL-13, and IL-17A in the sera of acute phase schistosomiasis were all significantly increased in the IUT and VEH groups compared with the UI group." (PMID 30258438, 2018). "Using inducible IL-4Rα deficient mice in the present study, we now dissected the role of IL-4/IL-13-mediated type 2 responses during acute and chronic murine schistosomiasis." (PMID 28827803, 2017). "Along with more extensive size of granulomas in the liver, the expression of TGF-β1 and IL-13 was significantly increased in murine schistosomiasis." (PMID 25590646, 2015). "The pathology characterized by granuloma formation around the eggs in the murine model of schistosomiasis is related to Th2 cytokines, such as IL-4 and IL-13." (PMID 25942636, 2015). "We performed haplotype analyses between the two IL13 SNPs and both chronic S. japonicum infection and late-stage schistosomiasis, adjusting for age, sex, HBV-infection and alcohol consumption." (PMID 26258681, 2015). "The aim of this study was to assess and compare the serum levels of total TGF-beta and IL-13 of patients with schistosomiasis with pulmonary arterial hypertension (PAH) and patients with schistosomiasis without PAH." (PMID 24886277, 2014). "Remarkably, for intestinal goblet cell hyperplasia in schistosomiasis signalling by IL-4/IL-13 is dispensible." (PMID 25398130, 2014). "An increase in Th2 responsiveness does occur with treatment of schistosomiasis with greater IL-4 and IL-13 in vitro responses to SWA being measured 7-wk, and beyond, post-treatment." (PMID 23556029, 2013). "Studies in schistosomiasis demonstrated that the development of fibrosis requires the production of the profibrotic cytokines IL-4 and IL-13." (PMID 21629648, 2011). "Because production of the soluble IL-13Rα2 is IL-4Rα-, IL-13Rα1-, and Stat6-dependent, these data combined with the schistosomiasis studies suggested that the Retnla−/− mice were developing stronger IL-4/IL-13 responses following infection." (PMID 19381262, 2009). "Fibroblasts are also important producers of the soluble IL-13Rα2, which can function as a decoy receptor for IL-13 and was recently shown to inhibit the development of fibrosis in schistosomiasis." (PMID 18369473, 2008). "In the course of experimental murine schistosomiasis and in a pulmonary granuloma model, blocking IL-13 notably reduces fibrosis but simultaneously increases IFN-γ production, followed by increased TNF production and necrosis of inflamed tissue, exacerbating lung and liver damage." (PMID 36016937, 2022). "However, our results showed that schistosomiasis uninfected individuals with IL-13-1112C variant (i.e genotypes CT and CC) had significantly higher IL-13 cytokine levels compared to the TT genotype implying that IL-13–1112 C variants may be protective against Schistosoma infections." (PMID 34048465, 2021).
schistosomiasis (continued). "Interleukin-13 (IL-13) is a protein secreted by many cell types and recognized as a type 2 immunity cytokine that plays an important role in a variety of diseases, including allergic inflammation, schistosomiasis, and tissue repair." (PMID 34604237, 2021). "IL-13 cytokine levels of the IL-13-1112 CC and CT variants were not significantly different (p = 0.310) from those with the TT variant for schistosomiasis infected." (PMID 34048465, 2021). "Additionally, it is well described that IL-4/IL-13-activated alternative macrophages are essential for surviving acute schistosomiasis." (PMID 23209848, 2012). "We could not establish an association between IL-13-1112C/T variants and susceptibility to schistosomiasis." (PMID 34048465, 2021). "Given the importance of IL-4 and IL-4 signaling for host protection, and knowing that basophils are a source of IL-4, we asked in this study whether IPSE/alpha-1, as a potent inducer of basophil IL-4/IL-13, might be involved in the control of inflammation in schistosomiasis." (PMID 30364177, 2018). "However, schistosomiasis caused by S. japonicum, the only human blood fluke that occurs in China, has not been studied for possible roles of IL13 SNPs, especially in patients with chronic or late-stage infection." (PMID 26258681, 2015). "To test whether IL-4/IL-13-induced arginase activity in macrophages was critical to the development of morbidity and mortality in schistosomiasis, we analyzed the survival of Arg1flox/flox and Arg1−/flox;LysMcre mice following infection with S. mansoni cercariae." (PMID 19360123, 2009). "The enhanced hepatic expression of IL‐2, IL‐5, IL‐13, or CXCL9 has been described in the context of schistosomiasis progression and generally in cirrhosis." (PMID 40751475, 2025). "This shift from a Th1- to Th2-skewed response significantly contributes to liver fibrosis in schistosomiasis, characterized by a decrease in IFN-γ (Th1 cytokine) and an increase in IL-4, IL-5, and IL-13 (Th2 cytokines) profiles." (PMID 39481080, 2024). "It is suggested that interleukin (IL)-13 and transforming growth factor (TGF)-beta play a role in the pulmonary vascular changes found in animal models of schistosomiasis." (PMID 24886277, 2014). "However, in schistosomiasis HF, in addition to TGF-β1, IL-13 is also a critical profibrotic factor, exerting its profibrogenic effects through activation of distinct SMAD proteins, indicating a more complex regulatory mechanism." (PMID 39363237, 2024). "During murine schistosomiasis, NKT cells could recognize glycolipids presented by CD1d on APCs, inducing the production of type 2 cytokines (IL-4, IL-5, IL-13) and influence the Th1/Th2 balance of the immune response." (PMID 36618421, 2022). "IL13, IL4, IL5, and STAT6 are also involved in regulation of the Th2 response to schistosomiasis." (PMID 33659002, 2021). "Participants with schistosomiasis (n = 20) had lower but not significant levels of IL-13, 75.64 (14.52–287.50) pg/mL compared to schistosomiasis uninfected group (n = 87) 89.88 (40.03–206.20) pg/mL; p = 0.481." (PMID 34048465, 2021). "Overall, it is known that IL-4 and IL-13 play redundant roles in the schistosomiasis granulomatous response, but IL-13 is not dependent on profibrotic cytokines or affected by Th1/Th2 cytokines." (PMID 32132991, 2020). "We show that in response to IL-4 and IL-13, Lyz2loIL-4Rα+ macrophages differentiate into an arginase 1-expressing alternatively-activated macrophage (AAM) population, which slows the development of lethal fibrosis in schistosomiasis." (PMID 25211233, 2014). "IL-13 induces proliferation and CD154 (CD40 ligand) expression in lung fibroblasts and is important in inducing fibrosis in Th2 mediated diseases such as schistosomiasis." (PMID 15987480, 2005).
schistosomiasis (continued). "In fact, the targeting of identified profibrotic cytokines (IL-5; IL-13) and growth factors (CTGF; TGF-β1 and VEGF) should be pursued in conjunction or as an alternative to current disease control measures to attempt to alleviate the fibrosis process during hepatosplenic schistosomiasis." (PMID 30546364, 2018). "The ability of the eggs to switch off the response to TGF-β in LX-2 cells supports the fact that fibrosis in schistosomiasis is considered to be independent of TGF-β and driven by IL-13 expression." (PMID 23840855, 2013). "It is also possible IL-13 acts during only early TH2 activation in an antigen-specific manner, but IgE levels specific against schistosomiasis antigens were not available in this Brazilian study." (PMID 22574126, 2012).